GNG7 (G protein subunit gamma 7)
Diseases named in the same sentence as GNG7 in open-access papers (continued):
Sharing a sentence is not in itself a finding about the gene and the disease.
tumor (continued). "Taken together, the results suggest that GNG7 is downregulated in GC and correlated with tumor progression." (PMID 36863706, 2023). "In previous reports, genes and methylation are suggested to be related to GNG7’s effect on suppressing tumor progression." (PMID 37704946, 2023). "In contrast, the expression level of ADHFE1 and GNG7 was significantly down-regulated in the tumor group." (PMID 36969015, 2023). "Of note, the results revealed that BIRC5, BUB1, and TPX2 were positively correlated with tumor purity, whereas GNG7 and SST were negatively correlated with tumor purity." (PMID 36863706, 2023). "The differences of GNG7 expression between tumor and normal tissues were analyzed in Oncomine database." (PMID 35281820, 2022). "The results showed that the expression of GNG7 was significantly correlated with tumor purity in 21 types of cancer, including COAD and READ." (PMID 35281820, 2022). "By analyzing the data from the UALCAN database, we found that the methylation level of GNG7 was significantly higher in the tumor group compared to that in the normal group." (PMID 36159963, 2022). "Moreover, the univariate Cox regression analysis model showed that GNG7 expression level was significantly associated with OS (HR: 0.702; 95% CI: 0.599-0.822; p < 0.001) similar to T stage, N stage, M stage and Pathologic stage as well Primary therapy outcome and Residual tumor." (PMID 36159963, 2022). "Of the infiltrated immune cells increased in LUAD with GNG7 high expression, B cell infiltration attracts our attention as the relatively less knowledge of this cell type in tumor immunotherapy currently." (PMID 36159963, 2022). "The correlation between GNG7 expression and tumor lymphocyte infiltration in COAD, READ and LIHC(TISIDB)." (PMID 35281820, 2022). "The low expression of GNG7 mRNA was related to the neoplasm histology grades (P = 0.045) and survival (P = 0.007) in PAAD patients." (PMID 34650124, 2021). "GNG7 downregulation has been observed in various cancers, and GNG7 acted as a tumor-suppressor gene involved in cancer progression." (PMID 34635014, 2021). "In conclusion, the current research reveals that GNG7 acts as a novel tumor suppressor, which can be upregulated by OST in BrCa." (PMID 33727922, 2021). "Recent findings reveal that G protein subunit gamma 7 (GNG7) is a tumor suppressor in ccRCC progression and has a potential to serve as a new biomarker or therapeutic target in ccRCC." (PMID 33686949, 2021). "As exhibited in, tumor weight and tumor volume were observably lower and smaller in the GNG7-overexpressed group than that in control group." (PMID 34635014, 2021). "Overexpression of GNG7 inhibit proliferation, metastasis and tumor formation ability of LUAD cells via in-activation Hedgehog pathway." (PMID 34635014, 2021). "Among them, DKK1, LDHA and MELTF are high-expressed in tumor tissues compared with tissue adjacent to carcinoma, but GNG7 is low-expressed." (PMID 33287749, 2020). "GNG7 gene was strongly suppressed in ccRCC tumor tissues as a result of promoter methylation and frequent gene mutation." (PMID 30945310, 2019). "TCGA ccRCC patient gene array showed that GNG7 mRNA expression was significantly repressed in tumor tissue in comparison to the normal tissue." (PMID 30945310, 2019). "Through the mapping of homozygous deletions in cell lines, GNG7 was identified as a possible tumor suppressor involved in the pathogenesis of Classical Hodgkin lymphoma." (PMID 27056891, 2016). "Further analysis is needed to investigate the tumor repressing role of GNG7 in a broader application and the mechanism by which GNG7 interacts and regulates MTOR signaling pathway." (PMID 27056891, 2016). "The methylation rate was 61% (20/33) on the promoter region of the GNG7 gene in primary HNSCC tumor samples and these tumors harbored high methylation values, mostly between 10 and 100%." (PMID 23403885, 2013).
tumor (continued). "Tumours with low GNG7 expression invaded deeper than those with high GNG7 expression (P<0.05), both in vivo and in vitro." (PMID 18219292, 2008). "In oesophageal tumour cell lines, the average expression level of GNG7 was quite low (relative expression: 0.11), similar to results obtained with clinical tumour samples." (PMID 18219292, 2008). "Tumour samples (relative expression: 0.096) expressed GNG7 at significantly lower levels than did normal samples (relative expression: 0.23) (P<0.0001)." (PMID 18219292, 2008). "GNG7, a key regulator of immune responses, could influence immune cell recruitment, cytokine secretion, and antigen presentation, thereby modulating tumor immune evasion." (PMID 40496619, 2025). "This pattern indicates that reduced GNG7 expression may contribute to uncontrolled cell proliferation, altered tumor suppressor responses, and metabolic reprogramming—hallmarks of cancer progression and immune evasion." (PMID 40496619, 2025). "Furthermore, our in vitro experiments have demonstrated that overexpression of GNG7 significantly inhibits cell proliferation, invasion, and migration, while promoting apoptosis, highlighting its potential as a tumor-suppressor gene in LUAD." (PMID 40496619, 2025). "As for newer therapeutic approaches such as CAR-T cell therapy, which involves modifying T cells to better target tumor cells, GNG7’s role in enhancing immune cell recruitment and activation may synergize with CAR-T cell therapy." (PMID 40496619, 2025). "In this context, GNG7’s ability to modulate the immune landscape could enhance tumor-specific immune responses, making it a valuable target for immunotherapies, including CAR-T cell therapies." (PMID 40496619, 2025). "By reducing the proliferative capacity and metastatic potential of LUAD cells, GNG7 could serve as a critical factor in controlling tumor progression and improving patient prognosis." (PMID 40496619, 2025). "This suggests that GNG7 might enhance the efficacy of immune checkpoint inhibitors by creating a more immunoreactive tumor environment." (PMID 40496619, 2025). "Moreover, the tumor prognostic model constructed based on GNG7-related immunomodulators was able to predict the 3-year and 5-year survival of CCRCC." (PMID 37704946, 2023). "As a tumor suppressor gene, GNG7 suppressed the growth of GC cells via cell cycle blockade and apoptosis induction and thus may be used as a potential biomarker and therapeutic target for GC." (PMID 36863706, 2023). "Previous experiments have shown that GNG7 expression reduces tumor volume in mice." (PMID 37704946, 2023). "Moreover, it was figured out based on clinicopathological analysis that, GNG7 expression gradually decreased with the increase in patient age and tumor stage." (PMID 37704946, 2023). "Then, in order to study the regulation mechanism of GNG7 on immune molecules in CRC, we further conducted an integrated analysis on the correlation between GNG7 expression and 28 tumor immune infiltrating cell subtypes as well as three subtypes of immunomodulators in TISIDB database." (PMID 35281820, 2022). "In addition, we respectively investigated the correlation of GNG7 with B cells in the tumor and normal tissues." (PMID 36159963, 2022). "As expected, elevated methylation level of GNG7 was observed in tumor tissues which may be responsible for the low expression of GNG7 in LUAD." (PMID 36159963, 2022). "In addition, we found that GNG7 expression was not only down-regulated in COAD and READ, but it was also associated with tumor histology, stage, lymph node metastasis according to the result in UALCAN." (PMID 35281820, 2022). "Also, GNG7 was confirmed as an essential autophagy-inducing agent and participated in inhibiting tumor progression through mTOR pathway." (PMID 36159963, 2022). "In addition, the relationship between GNG7 and tumor-related immune infiltration as well as gene marker sets of immune infiltration was investigated via TIMER, TISIDB and GEPIA." (PMID 35281820, 2022).
tumor (continued). "In addition, low expression of GNG7 was positively associated with the poor clinicopathological characteristics such as poor primary therapy outcome and high pathologic stage of LUAD, implying the tumor suppressive roles of GNG7 in LUAD." (PMID 36159963, 2022). "In order to identify whether GNG7 was an important regulator in CDR1as-mediated tumor suppressive effects, two different siRNAs were designed and transfected into AGS and MGC-803 cells to knockdown GNG7." (PMID 34221006, 2021). "In addition, there reported that GNG7 inhibited tumor progression through the mTOR pathway via inducing autophagy and cell death." (PMID 34635014, 2021). "Furthermore, rescue experiments demonstrated that GNG7 reintroduction weakened miR-19b-3p-mediated aggressive tumor phenotypes of LUAD cells." (PMID 34635014, 2021). "Overall, GNG7 acts as a novel tumor suppressor in BrCa, which may be a potential target for BrCa therapy." (PMID 33727922, 2021). "These in vitro data reveal that GNG7 impeded tumor proliferation and metastasis." (PMID 34635014, 2021). "The result showed that five genes (PRKCA, ADORA1, PPARGC1A, KL, GNG7) could be identified as potentially prognostic factors, and they have also been suggested as tumor suppressor genes." (PMID 31661791, 2019). "However, this fact does not invalidate our findings and the data of our study showing that the GNG7 gene is a promising candidate tumor suppressor gene and biomarker for HNSCC." (PMID 23403885, 2013). "These in vitro results were concordant with clinicopathologic data and support the hypothesis that GNG7 modulates tumour cell invasiveness." (PMID 18219292, 2008). "Although multivariate analysis did not disclose the statistical significance of GNG7 in predicting prognosis, several cases of tumour restricted in the oesophageal wall and with lower expression of GNG7 were useful in predicting poorer prognosis than the depth of tumour invasion." (PMID 18219292, 2008). "In 38 tumours with GNG7 suppression, 22 (57%) showed either LOH or promoter hypermethylation." (PMID 18219292, 2008). "Interestingly, this study demonstrated that GNG7 promoter hypermethylation occurred in advanced stage tumours as well as in early tumours." (PMID 18219292, 2008). "These five cases showed suppressed GNG7 expression in tumour tissue compared with normal tissue." (PMID 18219292, 2008). "Furthermore, GNG7’s ability to modulate antigen presentation could potentially improve the visibility of tumor cells to immune cells, promoting more robust immune responses against the tumor." (PMID 40496619, 2025). "Although the genes in (PRKAA2, GNG7, MYL3, NOS1, ADCY1, PLCB1, MYLK3, and MYLK4) the apelin/APJ signaling axis are found to be downregulated and might not be considered responsible in cdRCC progression, downregulation of GNG7 tells a different story due to its tumor‐suppressive activity." (PMID 40304310, 2025). "Hence, we hypothesized that GNG7 is a potential marker for predicting tumor immune microenvironment homeostasis." (PMID 35281820, 2022). "Moreover, most of studies indicate that GNG7 is a potential tumor suppressor." (PMID 34221006, 2021). "Besides, we also explored the function of GNG7 on BrCa cells and uncovered GNG7 as a tumor suppressor in BrCa, which may be a potential target for BrCa therapy." (PMID 33727922, 2021). "Our findings highlight the critical role of GNG7 in LUAD progression and its modulation of the tumor immune microenvironment." (PMID 40496619, 2025). "Moreover, GNG7 may also be involved in the modulation of immune checkpoint pathways, such as the PD-1/PD-L1 axis, indirectly enhancing T cell activity by reducing tumor-induced immune suppression." (PMID 40496619, 2025). "Consistent with the results of previous studies, our results showed that GNG7 mRNA and protein expression was down-regulated in CCRCC tissues, and the down-regulation degree was extremely related to tumor grade." (PMID 37704946, 2023).
tumor (continued). "Next, GNG7 expression profiles in six tumor-infiltrating immune cells (TIICs) and four immunosuppressive cells were obtained based on the TIMER database to further investigate the effect of GNG7 on the immune system." (PMID 37704946, 2023). "We can find that the expression of GNG7, MXRA7, ASB2, and PDGFD in tumor samples is significantly lower than that in normal samples, while the expression of RPS6KA1, CHMP4C, APOL1, and LYPD3 is reverse." (PMID 36225190, 2022). "In the tumor samples, F2, GLS2, IDO2, and PLAUR were shown to be significantly upregulated, while GNG7, PIK3CG, and ST3GAL6 were significantly down-regulated." (PMID 33619235, 2021). "In the independent GSE62452 dataset, the GNG7 and ADCY1 mRNA expression was incrementally downregulated with increasing tumor stages as well as neoplasm histology grades." (PMID 34650124, 2021). "Gain-of-function analysis showed that GNG7 overexpression inhibited proliferation and invasion of LUAD cell in vitro, and compromised tumor formation ability in vivo." (PMID 34635014, 2021). "Immunohistochemical results showed that GNG7 was positive in light yellow in adjacent tissues, while tumor tissues showed no positive staining." (PMID 37704946, 2023). "A study shows that low expression of GNG7 may induce the proliferation of LUAD tumor cells, increase the probability of invasion in vitro, and promote tumor growth and development in vivo." (PMID 37704946, 2023). "From the perspective of tumor staging, patients with distant metastasis also had lower GNG7 expression than those without distant metastasis." (PMID 37704946, 2023). "Based on previous studies and this research, it was reasonably speculated that GNG7 predicted the diagnosis and prognosis of CCRCC well, and it was also used as an important evaluation factor for tumor recurrence and early metastasis." (PMID 37704946, 2023). "Among these DEGs, CDKN2A, GNG7, GSDMD, and POLG are known tumor suppressors in GC." (PMID 36230863, 2022). "In the 24 pairs of samples including tumor and normal tissues, most expressions of GNG7 and MXRA7 in tumor tissues minus their expressions in normal samples were less than 0, indicating that the two most significant genes have higher expressions in normal tissues." (PMID 36225190, 2022). "In summary, this study revealed for the first time that GNG7 may be involved in regulating the immune microenvironment in LUAD and influence tumor development and patient prognosis at least partly by regulating the B cell infiltration." (PMID 36159963, 2022). "To further investigate the role of GNG7 in tumorigenesis ability in vivo, we used stable cell lines with GNG7-overexpressed and negative control to conduct mice xenograft tumor model." (PMID 34635014, 2021). "In summary, we identified GNG7 as a novel target for OST in BrCa and a potential tumor suppressor." (PMID 33727922, 2021). "In addition, the GNG7 and ADCY1 mRNA expression was incrementally downregulated with increasing neoplasm histology grades as well as tumor stages." (PMID 34650124, 2021). "Firstly, in order to explore whether GNG7 was dysregulated in LUAD, we determined the mRNA level of GNG7 in LUAD tissues and surrounding non-tumorous tissues through RT-qPCR." (PMID 34635014, 2021). "Consequently, we have reason to believe that GNG7 is closely correlated to immune cell infiltration in CRC, which guides us to speculate that GNG7 plays an important role in the tumor microenvironment and immune response of CRC." (PMID 35281820, 2022). "Furthermore, IHC assays revealed that GNG7 overexpression resulted in distinct suppression of Hedgehog signaling pathway-related molecules (GLI1, PTHCH1 and SMO) in tumor tissues obtain from xenograft tumor model." (PMID 34635014, 2021).
tumor (continued). "If GNG7 indeed facilitates tumor-specific immune responses, its expression could serve not only as a predictive biomarker for the efficacy of immunotherapy, but also as a potential therapeutic target to reverse resistance to immune checkpoint inhibitors (ICIs)." (PMID 40496619, 2025). "However, up to now, no existing study has reported whether GNG7 affects the occurrence and progression of tumor diseases by participating in the immune system." (PMID 37704946, 2023). "The GNG7 gene was the most marked, showing no methylation in normal mucosal samples and normal salivary rinses respectively, while 61% of primary HNSCC tumor samples were methylated." (PMID 23403885, 2013).